SUMO2 (small ubiquitin like modifier 2)
Description:
Ubiquitin-like protein that can be covalently attached to proteins as a monomer or as a lysine-linked polymer. Covalent attachment via an isopeptide bond to its substrates requires prior activation by the E1 complex SAE1-SAE2 and linkage to the E2 enzyme UBE2I, and can be promoted by an E3 ligase such as PIAS1-4, RANBP2, CBX4 or ZNF451. This post-translational modification on lysine residues of proteins plays a crucial role in a number of cellular processes such as nuclear transport, DNA replication and repair, mitosis and signal transduction. Polymeric SUMO2 chains are also susceptible to polyubiquitination which functions as a signal for proteasomal degradation of modified proteins. Plays a role in the regulation of sumoylation status of SETX.
Synonyms: Smt3B; SMT3H2; HSMT3
Tractability: Small molecule: a structure with a bound ligand is known. PROTAC: UniProt records ubiquitination sites on it; ubiquitination databases record sites on it; its protein half-life has been measured; a small molecule that binds it is known.
Gene: Protein-coding gene on chromosome 17 (75,165,586 to 75,182,991, reverse strand). Ensembl gene ENSG00000188612.
Subcellular location: Nucleus; Nucleus, PML body
Subcellular location (Human Protein Atlas): Nuclear bodies; Nucleoplasm; Calyx; Connecting piece; Flagellar centriole
Pathways (Reactome):
Metabolism of proteins: SUMO is conjugated to E1 (UBA2:SAE1); SUMO is proteolytically processed; SUMO is transferred from E1 to E2 (UBE2I, UBC9); SUMOylation of DNA damage response and repair proteins; SUMOylation of DNA replication proteins; SUMOylation of RNA binding proteins; SUMOylation of SUMOylation proteins; SUMOylation of chromatin organization proteins; SUMOylation of intracellular receptors; SUMOylation of transcription cofactors; SUMOylation of transcription factors
DNA Repair: Formation of Incision Complex in GG-NER; Processing of DNA double-strand break ends
Gene expression (Transcription): Regulation of endogenous retroelements by KRAB-ZFP proteins
Metabolism: Vitamin D (calciferol) metabolism
Gene Ontology:
Molecular function: protein binding; RNA binding; ubiquitin protein ligase binding; ubiquitin-like protein ligase binding
Biological process: positive regulation of proteasomal ubiquitin-dependent protein catabolic process; protein sumoylation
Cellular component: nuclear body; nucleoplasm; nucleus; PML body
Genetic constraint (gnomAD): Loss-of-function variants: 1 observed, 12.05 expected, observed/expected ratio (o/e) 0.083, 90% interval 0.028 to 0.39. The upper end of that interval is the gene's LOEUF score, 0.39, which puts it in group 1 of 6, group 1 being the genes least tolerant of losing a copy. Missense variants: 13 observed, 89.53 expected, observed/expected ratio (o/e) 0.15, 90% interval 0.094 to 0.23. Synonymous variants: 30 observed, 30.07 expected, observed/expected ratio (o/e) 1, 90% interval 0.75 to 1.35.
Homologues: Orthologues: chimpanzee SUMO2 (100% identical), dog SUMO2 (100% identical), guinea pig SUMO2 (100% identical), mouse Sumo2 (100% identical), pig SUMO2 (100% identical), rat Sumo2 (100% identical), Drosophila melanogaster Sumo (67% identical). Paralogues in human: SUMO3 (96% identical), SUMO4 (85% identical), NFATC2IP (32% identical).
Diseases named in the same sentence as SUMO2 in open-access papers:
SUMO2 is named in the same sentence as 106 diseases in open-access papers, as found by Europe PMC text mining. Sharing a sentence is not in itself a finding about the gene and the disease. The quoted sentences say what the papers report.
hepatocellular carcinoma (10 papers, 2014 to 2026). A malignant tumor that arises from hepatocytes. "Regarding the characterization of HuR SUMOylation in the HuH-7 human hepatoma cell line, V5-HuR was found to be particularly enriched after His6-tagged SUMO2 transient expression and downstream nickel-histidine affinity purification." (PMID 38507413, 2024). "Taken together, these findings indicate that short-term inflammatory stimulation increases the cytoplasmic SUMO2/3 level, which leads to cytoplasmic enrichment of p65 in hepatoma cells." (PMID 26993772, 2016). "To explore the association between SUMO2/3 and p65, we over-expressed SUMO2 and SUMO3 in hepatoma cells, respectively." (PMID 26458400, 2015). "Overexpression of SUMO-2 and the Uba2 E1 subunit has been correlated with poor survival of hepatocellular carcinoma patients." (PMID 24971752, 2014). "Our study further found that SUMO2/3 was involved in suppression of hepatoma cells proliferation." (PMID 26458400, 2015). "For instance, SAE1/2 is significantly upregulated in cancer tissues of hepatocellular carcinoma (HCC) patients, and the survival rate of HCC patients is related to the expression level of SUMO2." (PMID 38566133, 2024). "Moreover, we recently reported that SUMO2/3 can interact with p65, and SUMO2/3-mediated p65 SUMOylation promotes the stability of cytoplasmic p65 by antagonizing ubiquitination-mediated p65 degradation in the hepatoma cells." (PMID 26993772, 2016). "Additionally, SUMO2/3 over-expression inhibited the proliferation of hepatoma cells." (PMID 26458400, 2015). "In liver tissue, hepatocellular carcinoma exhibited elevated levels of SUMO1, SUMO2/3, UBC9, and SENP5 compared to normal controls." (PMID 41268439, 2025). "To this end, we co-expressed UBL proteins (i.e., MYC-DDK-tagged SUMO-1, HA-tagged SUMO-2, HA-tagged SUMO-3, and MYC-DDK-tagged ISG15) with tagged HBc (i.e., FLAG-tagged or HA-tagged, depending on the used UBL protein) in Huh7 hepatocellular carcinoma cells." (PMID 33256078, 2020). "The further study showed that SUMO2/3 over-expression decreased the proliferative ability of hepatoma cells, but did not affect the migration." (PMID 26458400, 2015). "Therefore, we want to know whether SUMO2/3 affects the proliferation and migration of hepatoma cells or not." (PMID 26458400, 2015).
gastric cancer (9 papers, 2014 to 2026). A primary or metastatic malignant neoplasm involving the stomach. "SUMO-2/3-modified NSUN2 reportedly promotes the progression of gastric cancer by regulating m5C mRNA methylation." (PMID 36532062, 2022). "In gastric cancer (GC) cells, a small ubiquitin-like modifier (SUMO)-2/3 interacts with the NSUN2 protein to promote its stability and mediate its import into the nucleus." (PMID 35562754, 2022). "Endogenous SUMO2/3 modifications on endogenous FOXC2 were further analyzed in the tissues obtained from the orthotopic gastric cancers in the mouse model." (PMID 25216525, 2014). "Additionally, SUMO-2/3 has been shown to stabilize NSUN2 and facilitate its nuclear transport in gastric cancer 48, while glucose-induced oligomerization and activation of NSUN2 promote TREX2 expression, suppressing cGAS/STING activation to regulate oncogenic activity in cancer cells." (PMID 41356184, 2026).
nasopharyngeal carcinoma (9 papers, 2018 to 2025). A carcinoma arising from the nasopharyngeal epithelium. "It is suggested that circRNF13 plays an essential role in the glucose metabolism programming of nasopharyngeal carcinoma (NPC) by stabling SUMO2 mRNA, increasing the SUMO and ubiquitination degradation of GLUT1." (PMID 38238756, 2024). "Interestingly, circRNF13 prolongs the half-life of SUMO2 mRNA by binding to the SUMO2 gene, which in turn inhibits the proliferation and metastatic ability of nasopharyngeal carcinoma." (PMID 37468464, 2023). "Moreover, circRNF13 is essential for the programming of nasopharyngeal carcinoma (NPC) glucose metabolism because it stabilizes SUMO2 mRNA, which increases GLUT1 ubiquitination and SUMO degradation." (PMID 40129920, 2025). "Circ-RNF13 prolongs the half-life of SUMO2 by binding to the 3′ untranslated regions (3′-UTR) of SUMO2 gene, which leads to sumoylation of GLUT1 and ubiquitination to regulate the AMPK-mtor pathway, ultimately promoting proliferation and metastasis of nasopharyngeal carcinoma (NPC)." (PMID 34881248, 2021).
breast carcinoma (7 papers, 2011 to 2026). "Modification of Sumo2 was associated with the progression and metastasis of breast cancer." (PMID 34497807, 2021). "Consistently, the upregulation of PML SUMO-2/3 modification has been observed in metastatic breast cancer cells." (PMID 33968766, 2021). "This fraction of Mad1 does not colocalize with nucleoli, but does show substantial colocalization with Myc and HA tagged SUMO1 and SUMO2 as well as endogenous SUMO1 in MDA-MB-231 breast cancer cells and in HeLa cervical cancer cells." (PMID 30948704, 2019). "We demonstrate that when T7-C/EBPbeta1 is expressed in breast cancer cells such as MDA231s, a ladder of higher molecular weight bands are observed with both a C/EBPbeta antibody and a SUMO-2/3 antibody, indicating sumoylation of C/EBPbeta1." (PMID 21980398, 2011). "Moreover, FASN was found SUMOylated in human breast cancer tissues and cell lines, and lack of SUMOylation caused by SUMO2 silencing reduced FASN protein stability." (PMID 32244364, 2020). "The high levels of SUMO2, ISG15, NEDD8, and UBD are related to worse prognosis outcomes in breast cancer." (PMID 41583390, 2026). "It was found that the global SUMO-2/3 modification was increased, but the SUMO2/3 modification of SAE2 was decreased in highly metastatic breast cancer cells." (PMID 33968766, 2021). "To demonstrate that SUMO2 protects FASN against proteasomal degradation, we treated the breast cancer cell lines with a protein synthesis inhibitor (CHX) and a proteasomal degradation inhibitor (MG132) in combination with SUMO2 silencing." (PMID 32244364, 2020). "SUMO2 is shown to protect FASN, where the combination of the protein synthesis inhibitor (cycloheximide) or proteasomal degradation inhibitor (MG132) with SUMO2 silencing, delays FASN degradation in breast cancer cell lines." (PMID 32872164, 2020).
Cerebral ischemia (5 papers, 2009 to 2024). Restriction of arterial blood supply to the brain associated with insufficient oxygenation to support the metabolic requirements of the tissue. "SUMO-1 levels were shown to be low in Parkinson's disease and Alzheimer's disease (AD) samples; while SUMO-2/3 was detected at high levels in cortex after cerebral ischemia." (PMID 19323834, 2009). "Collectively, these results conclusively confirm that cerebral ischemia induces the expression of SENP6 at both the RNA and protein levels and deconjugates SUMO2/3 chains from the ANXA1 protein." (PMID 34158860, 2021).
ischemia (5 papers, 2014 to 2025). A hypoperfusion of the BLOOD through an organ or tissue caused by a PATHOLOGIC CONSTRICTION or obstruction of its BLOOD VESSELS, or an absence of BLOOD CIRCULATION. "Previous studies have reported dynamic changes in protein SUMOylation during ischemic AKI, showing that SUMO1- and SUMO2/3-modified proteins increasing modestly after 30 min of ischemia but dramatically after 8 h of reperfusion, before declining during the 24-48-hour perfusion period." (PMID 41350286, 2025).
prostate carcinoma (5 papers, 2015 to 2024). A carcinoma that arises from epithelial cells of the prostate gland. "Using anti-SUMO-2/3 antibody, it was shown that heat stressed prostate cancer cells showed accumulation of SUMO-2/3 in the AR-binding regions of the target genes." (PMID 25705125, 2015). "Assessment of tissue from human prostate cancer patients indicates elevated mRNA levels of SENP1 and the SUMO2/3 deconjugating enzyme, SENP3." (PMID 27178176, 2016). "Additionally, double gene molecular subtype analysis with SUMO1, SUMO2, and XPO1 genes revealed survival outcome differences across molecular subtypes, further emphasizing NOP58’s critical role in prostate cancer biology and patient prognosis (Figures A1–C5)." (PMID 39494345, 2024). "DU145 cells, another prostate cancer cells with high metastatic potential, also exhibited the elevated expression of Snail and UBC9, and the mitogen-response sumoylation of Flot-1 by SUMO-2/3." (PMID 30631151, 2019). "The dual-gene molecular subtype analysis with SUMO1, SUMO2, and XPO1 genes revealed significant differences in survival outcomes across molecular subtypes, further emphasizing the potential impact of NOP58 on SUMOylation, a key post-translational modification, in prostate cancer." (PMID 39494345, 2024).
glioma (4 papers, 2020 to 2025). A benign or malignant brain and spinal cord tumor that arises from glial cells (astrocytes, oligodendrocytes, ependymal cells). "By suppressing SUMO2 expression, miR-212-5p has been demonstrated to control glioma cell migration, hyperplasia, and apoptosis." (PMID 40004224, 2025). "In glioma/glioblastomas, even at protein levels, SUMO2 is found to be significantly highly expressed than SUMO1." (PMID 34715855, 2021). "In this study, we found that PUM2 protein and SUMO2/3 protein were colocalized in glioma cells by laser scanning confocal microscopy." (PMID 32997416, 2020). "The purpose of this study is to clarify the SUMO2/3‐induced SUMOylation in glioma, as well as the expression and interaction of PUM2, CEBPD, and DSG2, and the role of these molecules in regulating VM of glioma." (PMID 32997416, 2020). "Hence, the use of SUMO2 inhibition strategies merits investigation in both high and low-grade astrocytomas/gliomas." (PMID 34715855, 2021). "Immunoprecipitation of endogenous NOP58 followed by immunoblotting with SUMO2 antibody in TAF15-knockdown cells and control cells indicated that endogenous NOP58 sumoylation was reduced after treating glioma cells with TAF15-targeted siRNAs." (PMID 37980347, 2023). "To investigate NOP58 sumoylation in glioma cells, we immunoprecipitated endogenous NOP58 then performed immunoblotting with small ubiquitin-related modifier 2 (SUMO2) antibody, revealing that endogenous NOP58 was sumoylated by SUMO2." (PMID 37980347, 2023). "However, the role of SUMO2/3, PUM2, CEBPD, and DSG2 in glioma VM has not been reported." (PMID 32997416, 2020).
heart failure (4 papers, 2020 to 2024). Inability of the heart to pump blood at an adequate rate to meet tissue metabolic requirements. "Studies have shown that the level of SENP5, which mainly deconjugates SUMO2/3, is elevated in heart failure." (PMID 34638970, 2021). "Importantly, both studies also reported a marked increase in SUMO2/3-mediated sumoylation in the hearts of human patients suffering from dilated, ischemic, or hypertrophic cardiomyopathy, pointing towards a broader pathogenic role of SUMO2 in the development of heart failure." (PMID 33037313, 2020). "On the other hand, SUMO2 and SUMO3 expression were found to be elevated in human patients with heart failure, and transgenic overexpression of SUMO2 in experimental models resulted in cardiomyopathy-associated heart failure." (PMID 39596076, 2024).
leukemia (4 papers, 2013 to 2022). A malignant (clonal) hematologic disorder, involving hematopoietic stem cells and characterized by the presence of primitive or atypical myeloid or lymphoid cells in the bone marrow and the blood. "Here we demonstrate that PML is essential for oxidative stress-driven partner SUMO2/3 conjugation in mouse ESCs (mESCs) or leukemia, a process often followed by their poly-ubiquitination and degradation." (PMID 36175410, 2022). "Further studies found the knockdown of CBX2 to facilitate the sumoylation activation of SUMO2/3, leading to the occurrence of leukemia." (PMID 34321009, 2021). "In addition, there is mounting evidence that the two major sites of SUMO-1 and SUMO-2/3 accumulation in the cell, the nuclear lamina and promyelocytic leukemia nuclear bodies (PML NBs), may play diverse roles in the DDR." (PMID 23554604, 2013).
viral infection (4 papers, 2013 to 2025). "We hypothesize that these discrepancies arise from distinct temporal dynamics of SUMO1 and SUMO2 modifications, which may have competing effects on the virus infection." (PMID 40521184, 2025). "Moreover, although details of SUMO2/3 conjugation in response to cellular stresses such as viral infection are quite well understood little is known about mechanisms and functions of selective SUMO1 up-regulation and its role during cellular transformation." (PMID 28253371, 2017). "We individually knocked out SUMO1, SUMO2, or SUMO3 in donor cells (293T) or target cells (A549-hACE2), to determine the impact of SUMOylation on Spike function during protein synthesis or viral infection." (PMID 40521184, 2025). "In the view of the fact that the perinuclear punctate distribution of SUMO2/3 has not been reported in other viral infections, we speculated that it may be important for SARS-CoV-2 infection." (PMID 40521184, 2025). "Moreover, we demonstrate that SUMO2 ameliorates NCAP-induced Tau pathology, highlighting the importance of the SUMOylation pathway as a target of intervention against neurotoxic insults, such as Tau oligomers and viral infection." (PMID 39000276, 2024).
cardiac hypertrophy (3 papers, 2016 to 2021). "Finally, as a proof of principle for an in vivo relevance of the proposed mechanism, we show that SUMO2 causes cardiac hypertrophy and contractile dysfunction in a sumoylation-independent manner in vivo, by means of AAV9 gene-transfer technology." (PMID 27767176, 2016). "Small ubiquitin-like modifier 2 (SUMO2) is the most efficient activator of calcineurin/NFAT signaling to induce cardiac hypertrophy." (PMID 34199773, 2021). "We recently reported SUMO2 as a potent activator of cardiac hypertrophy via activation of calcineurin-NFAT signaling." (PMID 33037313, 2020). "For this short period of overexpression, the observed effects support a relevant role for SUMO2 in calcineurin-driven cardiac hypertrophy and potentially cardiomyopathy in general." (PMID 27767176, 2016). "Nevertheless, we here report the induction of cardiac hypertrophy and contractile dysfunction as well as cardiomyopathy in mice overexpressing native SUMO2 via AAV9-mediated gene transfer." (PMID 27767176, 2016). "In conclusion, based on an unbiased screening approach, we linked SUMO2 to increased NFAT-activation, induction of hypertrophy-associated genes, and increased cellular and cardiac hypertrophy, both, in vitro and in vivo." (PMID 27767176, 2016). "We found SUMO2 as an interesting candidate for modulating the calcineurin-NFAT driven cardiac hypertrophy via sumoylation independent binding." (PMID 27767176, 2016). "Furthermore, we show that not only SUMO2-dependent sumoylation, but SUMO2 expression per se is enhanced in two important mouse models of cardiac hypertrophy and pressure overload." (PMID 27767176, 2016). "In broader terms, these findings reveal an unexpected role for SUMO2 in cardiac hypertrophy and cardiomyopathy, which may open the possibility for therapeutic manipulation of this pathway." (PMID 27767176, 2016). "Given the strong activation of NFAT-signaling in NRVCM, C2C12 and HEK cells, and the upregulation of SUMO2 in mouse models of cardiac hypertrophy as well as in human patients suffering from DCM or ICM, we investigated the potential phenotypic and molecular effects of SUMO2 in NRVCM." (PMID 27767176, 2016).
cardiomyopathy (3 papers, 2016 to 2024). A disease of the heart muscle or myocardium proper. "Of note, SUMO2 has also been implicated in human cardiomyopathy where diminished sumoylation of Lamin A results in accelerated cell death." (PMID 27767176, 2016). "In addition, increased SUMO2-mediated sumoylation in human cardiomyopathy patients and in mouse models of cardiomyopathy were observed." (PMID 27767176, 2016).
cervical cancer (3 papers, 2015 to 2019). A primary or metastatic malignant neoplasm involving the cervix. "A recent screen for sumoylated proteins after heat shock showed that endogenous La was modified by SUMO-2 in the human cervical cancer cell line HeLa." (PMID 27224031, 2016). "The protein is SUMO2 is also modified variety of cellular proteins leads to the alterations in many signaling pathways associated with their target proteins, but its role in cervical cancer is not clear." (PMID 26308848, 2015).